HTT (huntingtin)
Diseases named in the same sentence as HTT in open-access papers (continued):
Sharing a sentence is not in itself a finding about the gene and the disease.
neurodegenerative disease (continued). "HD is a rare autosomal­dominant neurodegenerative disease caused by detrimental aggregation­prone HTT mutants (mHTT) with an aberrant expansion of cysteine, adenine, and guanine (CAG) trinucleotide repeats within exon 1 of the HTT gene." (PMID 33990205, 2021). "Also, HSP70 and HSP40 (DnaJ) functionally interact with soluble mutant huntingtin oligomers suppressing unfolded protein toxicity and thus protect against neurodegenerative disease." (PMID 31396262, 2019). "Although HD is essentially a neurodegenerative disease, a mutant huntingtin aggregation in the nucleus and mitochondria of cardiomyocytes was observed, so it might be worth investigating possible cardiac pathology in this disease." (PMID 30028085, 2018). "HD is a monogenic neurodegenerative disease displaying widespread transcriptional deregulation as a key feature resulting from a CAG expansion in the HTT gene on chromosome 4p16.3 leading to the production of mutant Htt protein containing a prolonged polyQ tract that is prone to aggregation." (PMID 28499347, 2017). "If endogenous mouse HTT is recruited into the inclusions then the presence of heterozygous protein differences is known to slow aggregation of the cognate proteins in other neurodegenerative diseases where protein inclusions are present in the disease, for instance in prion-related disease." (PMID 26691352, 2015). "Furthermore, vaccination is also effective experimentally in other mouse models of neurodegenerative diseases, by reducing the accumulation of toxic proteins aggregates such as amyloid β, tau, prion protein and huntingtin." (PMID 25886309, 2015). "HD is a fatal hereditary neurodegenerative disease caused by a CAG repeat expansion mutation in exon 1 of the Huntingtin (Htt) gene, which results in a toxic polyglutamine (polyQ) stretch in the encoded Huntingtin (Htt) protein." (PMID 23349832, 2013). "The same correlation is observed for oxidative and protein stress tolerance and clearance of toxic huntingtin fragments in a yeast model for neurodegenerative diseases, suggesting that lifespan extension by increased proteasome capacity is caused by improved protein homeostasis." (PMID 21931558, 2011). "In neurodegenerative diseases increased p62 is a common feature detected in inclusion bodies containing polyubiquitinated protein aggregates, including Lewy bodies in PD, neurofibrillary tangles in AD, and Huntingtin aggregates in HD." (PMID 18682838, 2008). "The use of saliva for biomarker research in neurodegenerative diseases has been growing in past years, with previous studies already focused on its potential utility in HD, including our previous study showing that the huntingtin protein is uniquely processed in saliva, compared to blood." (PMID 39849121, 2025). "In the context of neurodegenerative diseases, proteostasis loss substentially contributes to the abnormal accumulation of various pathological proteins, including amyloid-beta (Aβ), hyperphosphorylated tau, α-synuclein (α-syn), TAR DNA binding protein-43 (TDP-43), huntingtin (HTT)." (PMID 40059211, 2025). "The antiapoptotic role of HTT and the observation that mutant HTT induces apoptosis suggest that apoptosis may also be another common pathway shared in polyQ-related neurodegenerative diseases." (PMID 33425926, 2020). "Therefore, it is likely that misfolded protein in neurodegenerative diseases, like α-synuclein in PD and huntingtin in HD, might also possess the similar property in regulating TFEB expression and cellular distribution." (PMID 28769785, 2017). "However, Hsp70 over-expression in neuronal cell cultures and mouse models of some neurodegenerative diseases have demonstrated a beneficial reduction in abnormal protein aggregation, such as amyloid peptides, tau protein, huntingtin and α-synuclein fibril formation." (PMID 25153885, 2014).
neurodegenerative disease (continued). "Furthermore, the same approach as the one taken here may be used to study the role of aggregation of other proteins, e.g. Huntingtin, α-synuclein, β-amyloid, in other neurodegenerative diseases." (PMID 24252504, 2013). "HD represents one of the most devastating hereditary neurodegenerative diseases, resulting from a CAG repeat expansion in the huntingtin (HTT) gene that produces a mutant huntingtin protein (mHTT) with an elongated polyglutamine tract." (PMID 41596628, 2026). "In neurodegenerative diseases, CRISPR has been used to selectively knock out the mutant form of the huntingtin (HTT) gene, reducing the toxic protein burden and mitigating oxidative stress in neuronal cells." (PMID 39334768, 2024). "This review elucidates the critical link between neurodegenerative diseases and specific posttranslational modifications, focusing on Tau, APP, α‐synuclein, Huntingtin protein, Parkin, DJ‐1, and Drp1." (PMID 39105197, 2024). "TNTs have been proposed to play a key role in neurodegenerative diseases and are involved in the spread of aggregated proteins such as tau, APP, and huntingtin by an intracellular pathway instead of a soluble-mediated mechanism." (PMID 37396786, 2023). "The prion-like proteins such as huntingtin fibrils and TDP-43 involved in neurodegenerative diseases are shown to trigger TNT formation in neuronal cells." (PMID 37396786, 2023). "Neurodegenerative diseases are characterized by abnormal accumulation of misfolded proteins including α-synuclein, tau, TDP-43 and Huntingtin in the CNS." (PMID 36256604, 2022). "For example, by modulating linear ubiquitination, LUBAC induces proteasomal degradation of aberrantly aggregated proteins, including mutant Huntingtin, Ataxin-3, SOD1, and TDP-43, which all are involved in neurodegenerative disease." (PMID 34737388, 2022). "HD is a dominantly inherited neurodegenerative disease resulting from a CAG trinucleotide repeat expansion in exon 1 of the Huntingtin gene (>35 CAG repeats), leading to expression of mutant Huntingtin (mHtt) protein with an elongated polyglutamine tract." (PMID 31551669, 2019). "Moreover, since elevated proteasome capacity results in improved clearance of toxic huntingtin fragments in a yeast model for neurodegenerative diseases, we speculate that the observed lifespan extension originates from prolonged elimination of damaged proteins in old mother cells." (PMID 21931558, 2011). "The relationship between SGs and neurodegenerative diseases has been suggested by previous experiments demonstrating that PrP, SMN and huntingtin co-localize with SG proteins in inclusions." (PMID 20948999, 2010). "However, under the pathological conditions of various neurodegenerative diseases, we have identified that the abnormal expression of proteins such as Tau, amyloid-β, α-synuclein, huntingtin, and TDP-43 is a primary driver of neurodegenerative disease onset." (PMID 40001986, 2025). "In recent years, several proteins involved in neurodegenerative diseases, such as Tau, TDP43, FUS, huntingtin, and hnRNPA1, have been reported to form cytosolic condensates, and efforts have been made to describe the physiological and pathological consequences of this phenomenon." (PMID 37585526, 2023). "HTT, neurofilament heavy chain (NF‐H), Tau (MAPT), FUS, TDP‐43, HNRNPA1, HNRNPD, RPL7 and actin (ACTB, found aggregated in Hirano bodies in several neurodegenerative diseases; Hirano, 1994), were selectively aggregated upon RNase A/T1 treatment of human neuronal lysates." (PMID 32945072, 2020). "Importantly, each neurodegenerative disease has typical aggregating proteins, such as amyloid β (Aβ) in AD, tau in AD and FTD, α-synuclein in PD, TAR DNA-binding protein 43 (TDP-43) in ALS and FTD, and mutant huntingtin in HD." (PMID 36726375, 2023). "Therefore, small molecules designed to treat neurodegenerative diseases should selectively lower the levels of mHTT but not HTT." (PMID 36209136, 2022).
neurodegenerative disease (continued). "Unlike normal aging, neurodegenerative diseases (due to genetic or environmental influences) can lead to misfolding and accumulation of native cerebral proteins, such as prion, tau, β-amyloid, α-synuclein, and huntingtin." (PMID 33005144, 2020).
neurological disorder (43 papers, 2011 to 2025). "It is a devastating and incurable neurological disorder caused by a trinucleotide repeat expansion (CAG) in the gene encoding the huntingtin (HTT) protein, which results in an expanded polyglutamine tract at the N-terminus of the HTT protein." (PMID 32213859, 2020). "HD is an inherited neurological disorder caused by a mutation in IT15 gene that encodes huntingtin protein (Htt) predominantly found in neurons." (PMID 29692728, 2018). "Amyloid β protein and huntingtin, genes implicated in other neurological diseases and reduced neuronal function in aged humans, were tested for DE with qPCR." (PMID 29996779, 2018). "Huntington's disease (HD) is an inherited neurological disorder caused by abnormal expansion of a CAG (cytosine-adenine-guanine) repeat within exon 1 of the huntingtin (Htt) gene, located on chromosome 4." (PMID 29033839, 2017). "Huntingtin is examined with particular attention as it is associated with the most frequent and the most investigated of the neurological diseases caused by polyQ expansion." (PMID 24961702, 2014). "R6/2 transgenic mice expressing the first exon of human huntingtin, which encodes about 130 glutamine residues flanked by 17 N-terminal and 52 C-terminal residues develop neurological disease and neuronal inclusions." (PMID 24961702, 2014). "Conversely, it has been proposed that CAG-repeat containing proteins, in which repeat expansion causes neurological disorders, function in DNA repair: examples include Huntingtin protein (HTT), the product of the huntingtin gene mutated in HD, which is recruited by ATM to sites of DNA damage." (PMID 33669593, 2021). "Recently, accumulating studies have revealed that pathological protein associated with neurological diseases, such as β-amyloid, α-synuclein, and Huntingtin, could undergo palmitoylation, highlighting the crucial roles of protein palmitoylation in the onset and development of neurological diseases." (PMID 39991624, 2025). "Therefore, the removal of the mutated HTT protein has important therapeutic implications for HD, and identifying a treatment for any one neurological disease will have broad implications for the development of treatments for a large number of patients with neurological diseases." (PMID 38666293, 2024). "Other lethal neurological diseases are also caused by accumulation of denatured toxic proteins including SOD1 G93A in ALS and Huntingtin in HC." (PMID 34252884, 2021). "Huntington’s disease (HD) is a progressive, dominantly inherited neurological disorder caused by an abnormal expansion of polyglutamine (polyQ) repeat within the Huntingtin (Htt) protein with no disease modifying treatments." (PMID 26728250, 2016). "The potential link between DISC1, huntingtin and their interacting partners may open new areas of research into the effects of pathway dysregulation in severe neurological disorders." (PMID 21298101, 2011).
cancer (30 papers, 2013 to 2025). A tumor composed of atypical neoplastic, often pleomorphic cells that invade other tissues. "Taken together these results show that polyQ-huntingtin expression in cancer cells is associated with enhanced migratory and invasive behaviours, and an elevated resistance to anoikis." (PMID 23300147, 2013). "We thus propose a link between molecular pathways underlying neurodegeneration, cancer tumourigenesis and metastasis through mutant huntingtin." (PMID 23300147, 2013). "Interestingly, the HD-causing protein huntingtin, including its wild-type form, has been suggested to regulate cellular processes involved in tumorigenesis and cancer progression." (PMID 36253622, 2023). "Two of them (rs117867773 and rs28585580) have been poorly studied, but variants in HTT and MLH1 have been shown to have pathogenetic significance in the development of HD and cancer, respectively." (PMID 40843670, 2025). "Murmann A.E., Gao Q.Q., Putzbach W.E., Patel M., Bartom E.T.,Law C.Y., Bridgeman B., Chen S., McMahon K.M., Thaxton C.S.,Peter M.E. Small interfering RNAs based on huntingtin trinucleotiderepeats are highly toxic to cancer cells." (PMID 36923482, 2023). "Huntingtin (HTT) is one of the target genes of miR-146-a and regulates various cancer cell activities." (PMID 33282738, 2020). "Our results showed that the overexpressed miR-146a in OSCC possibly targets the HTT gene to induce cancer cell migration and invasion, suggesting the role of miR-146a and HTT in OSCC progression, metastasis, and invasion." (PMID 33282738, 2020). "Overexpressed miR-146a in OSCC targets the HTT gene and enhances cancer cell migration/invasion unraveling the possible role of HTT in miR146a-mediated OSCC cell migration and invasion." (PMID 33282738, 2020). "For the first time, our study reported the overexpression of miR-146a in OSCC as an inducer of cancer cell migration and invasion possibly via targeting the HTT gene." (PMID 33282738, 2020). "Knockdown of HTT in OSCC cells enhanced the cancer cells migration and invasion, and miR-146a knockout OSCC mice showed higher expression of HTT and inhibited the cancer aggressiveness and epithelial damage." (PMID 33282738, 2020). "In this study, we found that knockdown of the HTT gene in OSCC cells robustly enhanced the cancer cell migration and invasion in vitro." (PMID 33282738, 2020). "We suggest here that the reported huntingtin functions depend on the cell type and the cell context being studied as we found that mutant huntingtin conferred resistance to anoikis to cancer cells while it renders them more sensitive to Trastuzumab treatment." (PMID 23300147, 2013). "We had access to cancer biopsies from HD patients and used immunohistochemistry with an antibody recognizing both the wild-type and mutant forms of huntingtin." (PMID 23300147, 2013). "Some recent studies have reported the role of HTT in cancer development and progression." (PMID 33282738, 2020). "However, this interference was demonstrated in mouse embryos or embryo-derived cells carrying two mouse mutHTT alleles with 111 CAGs (HdhQ111/Q111 knock-in mouse model) or in human cancer cells (Hela) overexpressing an N-terminal fragment of human HTT with 68 CAGs." (PMID 26863614, 2016). "OLFM4, Histone H3, HTT activate HSPA5, an important molecule that tends to lead to cancer metastasis." (PMID 38304289, 2023). "Assuming that HTT expansion is the main factor in HD, most studies on the inverse comorbidity of HD and cancer are focused on the HTT gene, the huntingtin protein, and CAG repeats." (PMID 37298337, 2023). "Some of these genes (e.g. CENPF, MLKL, TFDP1, MCF2L) have a known influence on cancer, while others (e.g. NUP54, BBS1 and HTT) have been superficially studied under the tumoral context." (PMID 34316711, 2021).
genetic disorder (23 papers, 2011 to 2025). "Huntington’s disease (HD) is a devastating genetic disorder caused by an expansion of trinucleotide repeat (CAG) in the first exon of the Huntingtin gene (Htt)." (PMID 38374466, 2024). "HD is a genetic disease caused by overexpression of the huntingtin coding gene, new research suggests that an imbalance in gut microbiota dysregulates the cytokine levels and excessive production of hydrogen sulfide that negatively affects gut health." (PMID 37110506, 2023). "Described in 1872 by George Huntington, HD is a genetic and hereditary disease, due to the mutation of the gene IT15, resulting in the repeat expansion of CAG trinucleotide, coding for the huntingtin protein (mHtt)." (PMID 34371733, 2021). "In case of HD, a polyQ expansion at the N-terminus of the huntingtin protein is the cause of this mono-genetic disease." (PMID 32424160, 2020). "HD is a genetic disorder caused by a trinucleotide (CAG) repeat expansion in the gene encoding for huntingtin (HTT) on chromosome 4p16.3." (PMID 27578922, 2016). "Although the cause of HD is well described—HD is a genetic disorder caused by a trinucleotide (CAG) repeat expansion in the gene encoding for huntingtin (HTT) on chromosome 4p16.3—the ultimate cause of neuronal death is still uncertain." (PMID 27578922, 2016). "Huntington's disease is a genetic disorder characterized by an increased number (over 40) of glutamine amino acids at the N-terminus of the huntingtin protein (Htt), which affect the medium spiny neurons." (PMID 28468938, 2017). "Genes in the regions include well-studied imprinted loci (e.g. Plagl1/Zac1), homologues of human genes involved in adaptations (e.g. alpha-amylase genes) or in genetic diseases (e.g. Huntingtin and Parkin)." (PMID 22956910, 2012). "This genetic disorder is caused by the expansion of a CAG trinucleotide repeat in exon 1 of the huntingtin gene (HTT), which is translated into polyglutamine residues (polyQ) in the huntingtin protein (HTT)." (PMID 24324398, 2013).
hereditary neurodegenerative disorder (20 papers, 2012 to 2026). "HD is a hereditary neurodegenerative disorder primarily caused by a mutation in the huntingtin (HTT) gene, which results in an expanded cytosine-adenine-guanine (CAG) trinucleotide repeat." (PMID 40003898, 2025). "BackgroundHuntington's Disease (HD) is a hereditary neurodegenerative disorder caused by a cytosine-adenine-guanine (CAG) repeat expansion (CAG > 35) in the Huntingtin (HTT) gene." (PMID 41406155, 2025). "HD is a hereditary neurodegenerative disorder caused by an expanded CAG repeat in the huntingtin (HTT) gene, leading to the production of mutant huntingtin protein (mHTT)." (PMID 39072992, 2024). "Huntington’s disease (HD) is an incurable, hereditary neurodegenerative disorder caused by a CAG trinucleotide repeat expansion in exon 1 of the Huntingtin (Htt) gene." (PMID 35869509, 2022). "HD is a rare and rapidly progressive hereditary neurodegenerative disorder caused by CAG repeat expansions in the Huntingtin (HTT) gene, accumulation of its mutant protein (mHTT) and consequent detriment to glial health and neuronal survival." (PMID 33309801, 2021).
autosomal dominant disease (18 papers, 2013 to 2025). Autosomal dominant form of disease. "HD is an autosomal dominant disease caused by an expanding poly-Q tract in the huntingtin (HTT) protein." (PMID 34727995, 2021). "HD is an inherited neurodegenerative disorder, an autosomal dominant disease caused by a CAG trinucleotide repeat expansion in exon 1 of the gene encoding huntingtin (HTT)." (PMID 31600883, 2019). "HD is an autosomal dominant disease resulting from a mutation in the gene coding huntingtin (HTT) on chromosome 4." (PMID 28912682, 2017). "HD is an autosomal dominant disease characterized by mutations in the huntingtin (HTT) gene." (PMID 39127627, 2024). "This autosomal dominant disease is characterized by variable length CAG trinucleotide repeats, the transcript encoding the huntingtin protein (HTT)." (PMID 34639150, 2021). "Genetically, HD is an autosomal dominant disease caused by a CAG repeat expansion in the HTT (huntingtin) gene, which translates into a polyglutamine tract in HTT protein." (PMID 25271153, 2014). "HD is an autosomal dominant disease caused by a mutation in the Huntingtin gene due to an expansion of the CAG trinucleotide repeat to more than 35 repeats, leading to an abnormal huntingtin protein (HTT) with an expanded polyglutamine in its N-terminal domain, and toxic gain of function." (PMID 30513609, 2018). "HD is an autosomal dominant disease with characteristic cytosine, adenine, and guanine (CAG) trinucleotide repeats on the short arm of chromosome 4p16.3 within the huntingtin (HTT) gene, leading to the production of a mutant huntingtin protein (mHTT)." (PMID 38994995, 2024).